S100A9 (S100 calcium binding protein A9)
Diseases named in the same sentence as S100A9 in open-access papers (continued):
Sharing a sentence is not in itself a finding about the gene and the disease.
pterygium (6 papers, 2009 to 2023). A wedge-shaped fibrovascular lesion arising from the bulbar conjunctiva and extending to the cornea. "The S100A8 and S100A9 are calcium binding secreted proteins that have been previously identified to be up-regulated in various ocular surface conditions including pterygium, dry eye, meibomian gland dysfunction and corneal neovascularisation." (PMID 24825356, 2014). "Previously, our group has reported that S100A8 and S100A9 were localized in the superficial layer of both pterygium and normal conjunctiva epithelium, with higher levels in pterygium than uninvolved conjunctiva." (PMID 24825356, 2014). "The most abundant complementary DNAs from pterygium include clusterin, keratins 13 (Krt13) and 4 (Krt4), S100A9/calgranulin B, and spermidine/spermine N1-acetyltransferase (SAT1)." (PMID 19956562, 2009). "A similar staining pattern was also observed with the expression of S100A8 and S100A9 in the uninvolved conjunctiva and pterygium." (PMID 19223989, 2009). "In summary, a change in level of expression was detected in S100A6, S100A8, and S100A9 in pterygium tissue relative to the normal conjunctiva." (PMID 19223989, 2009). "Our findings, which showed an increased expression of S100A8 and S100A9 in the superficial layer of pterygium epithelium, support the notion that S100 proteins are centrally involved in cell maturation processes." (PMID 19223989, 2009). "Higher levels of S100A6, S100A8, and S100A9 expressions were detected in the pterygium tissue relative to normal conjunctiva." (PMID 19223989, 2009). "Several of the genes expressed most abundantly in excised pterygium, particularly S100A9 and SAT1, have roles in cell migration." (PMID 19956562, 2009). "S100A8 and S100A9 were localized in the superficial layer of both pterygium and normal conjunctiva epithelium, with higher levels in pterygium than uninvolved conjunctiva." (PMID 19223989, 2009). "Higher expression levels of S100A6, S100A8, and S100A9 were observed in the pterygium tissue when compared to normal conjunctiva and it has been postulated that these proteins may be associated with the pterygium formation." (PMID 30673862, 2019). "The S100A8 and S100A9 have been found to be up-regulated in pterygium tissue." (PMID 24825356, 2014). "However, S100A6, S100A8, and S100A9 transcripts were upregulated (p<0.05) in pterygium relative to normal conjunctiva." (PMID 19223989, 2009). "However, expression of S100A6, S100A8, and S100A9 were markedly greater in the pterygium tissue compared to the uninvolved conjunctival tissue." (PMID 19223989, 2009). "Several DEGs in pterygium and pSS tissues were identified from the datasets, and five hub genes (IL1R1, ICAM1, IRAK1, S100A9, and S100A8) were finally screened out." (PMID 36768371, 2023). "Compared with the healthy control conjunctiva, the expression of five hub genes (IL1R1, ICAM1, IRAK1, S100A9, and S100A8) in pterygium or pSS samples was statistically significant (p < 0.05)." (PMID 36768371, 2023). "We identified a shared gene signature (IL1R1, ICAM1, IRAK1, S100A9, and S100A8) between pterygium presence and pSS." (PMID 36768371, 2023). "We further investigated the ability of S100A8, S100A9 and S100A8/A9 to regulate the expression of a panel of genes involved in pterygium pathology using primary cell cultures." (PMID 24825356, 2014). "In pterygium tissue, S100A6 expression increased 2.30 fold, S100A8 increased 3.36 fold, and S100A9 increased 4.01 fold relative to normal conjunctiva." (PMID 19223989, 2009). "S100A4, S100A6, S100A8, S100A9, and S100A11 gene transcripts were detected in conjunctiva and pterygium tissues." (PMID 19223989, 2009). "Our investigation revealed that S100A4, S100A6, S100A8, S100A9, and S100A11 are expressed in both the normal and pterygium epithelia." (PMID 19223989, 2009). "Immunofluorescent staining detected the presence of S100A4, S100A6, S100A8, S100A9, and S100A11 in normal human conjunctival and pterygium epithelia." (PMID 19223989, 2009).
pterygium (continued). "Western blot and RT–PCR confirmed the presence of S100A4, S100A6, S100A8, S100A9, and S100A11 in pterygium and conjunctiva tissue." (PMID 19223989, 2009). "Recently, our laboratory detected a marked increase in the expression of S100A8 and S100A9 in the tear fluid of pterygium patients relative to the normal conjunctiva." (PMID 19223989, 2009). "Since these proteins are expressed during terminal differentiation and are associated with intermediate filaments, a functional role in the reorganization of the cytoskeleton during hyperproliferative ocular surface disease such as pterygium may be assumed for S100A8 and S100A9." (PMID 19223989, 2009).
tendinopathy (6 papers, 2017 to 2024). "This chemotaxis and cytokine modulation are particularly prominent in the early stages of tendinopathy, establishing a mechanistic link between S100A8 and S100A9 proteins and RC tendinopathy development." (PMID 38248784, 2024). "Our data confirms the presence of S100A8 and S100A9 in tendinopathy and suggests they actively contribute to pathological proceedings in the early stages of disease." (PMID 30728384, 2019). "Our study has established the presence of S100A8 and S100A9 in a human model of tendinopathy, most notably in the early stages of disease." (PMID 30728384, 2019). "We next noted significantly greater protein expression of the alarmin molecules S100A8 and S100A9 in the early tendinopathy group compared with the control group (p < 0.05)." (PMID 30728384, 2019). "This study investigates protein expression in diseased tendon tissues before and after treatment and reveals pro-inflammatory roles for HIF-1α and S100A9 in tendinopathy." (PMID 28761710, 2017). "Furthermore, S100A8 and S100A9 are products of neutrophils and monocytes and are known to modulate the early stromal microenvironment during the development of tendinopathy and to influence the composition of the inflammatory cell infiltrate." (PMID 35039073, 2022). "Semi quantitative analysis again suggested that S100A9 (9% early tendinopathy, 5% late tendinopathy, % of cells stained positive) was more frequently expressed that S100A8 (4% early tendinopathy, 1% late tendinopathy, % of cells stained positive) in tissue biospies." (PMID 30728384, 2019). "Recent investigations have established tendinopathy as an alarmin-mediated pathology thus we sought to characterize the expression of S100A8 and S100A9 in human tendinopathy and explore their biological significance in the context of inflammation and matrix regulation." (PMID 30728384, 2019). "This implies that S100A8/S100A9 modulates the inflammatory profile through a positive feedback mechanism, involving increased recruitment of leukocytes and the release of pro-inflammatory cytokines from tenocytes, sustaining the inflammatory response in the early stages of tendinopathy." (PMID 38248784, 2024). "During tendinopathy conditions, the inductive expression and secretion of S100A8 and S100A9 affect the activation of local tenocytes, boosting immune cell recruitment to the injured site and altering the stromal microenvironmental cue." (PMID 35892571, 2022). "Specifically, S100A9 and HIF-1α may have pro-inflammatory effects in tendon disease, nuclear IL-33 may be protective against pro-inflammatory stimuli and HMGB1 may have a potential role in tendon healing." (PMID 28761710, 2017). "Quantifying the expression study of alarmin in diseased supraspinatus tendons suggested that S100A9 and HIF-1α may have pro-inflammatory effects in tendon disease, nuclear IL-33 may protect against pro-inflammatory stimuli, and HMGB1 may play a role in tendon recovery." (PMID 35892571, 2022). "Moreover, there are little data regarding the potential roles of S100A9 and HMGB1 in tendinopathy." (PMID 28761710, 2017). "We observed greatest significant upregulation of S100A8 and S100A9 in early tendinopathy and a relative absence of S100A8 mRNA expression in late tendinopathy suggesting these alarmins are key regulators in the early stage of disease." (PMID 30728384, 2019).
type 1 diabetes (6 papers, 2021 to 2026). "For CD2 and CD3, the human genes of S100A9 (calcium binding protein A9) and IGHG1 (immunoglobulin heavy constant gamma 1) have previously identified as genes of interest as is the case with REG1A (pancreatic stone protein) for type-1 diabetes." (PMID 40893175, 2025). "(2013) reported that S100A8/S100A9 acted through the receptor for advanced glycation end-products (RAGE) on CMPs to promotegranulocyte–macrophage colony-stimulating factor (GM-CSF) production that in turn stimulated GMP proliferation and myelopoiesis in type 1 diabetic mice and apoE−/− mice." (PMID 36866528, 2023).
type 2 diabetes (6 papers, 2013 to 2025). "Serum levels of S100A9 and calprotectin were higher in T1D patients compared to healthy controls, and correlated with the progression of diabetic retinoptahy in T2D patients, but also with insulin resistance/type 2 diabetes, metabolic risk score, and fat cell size caused by obesity." (PMID 32582175, 2020). "Therapeutic strategies to reduce neutrophilia and NETosis are aimed at disruption of S100A8/S100A9 signalling or their downstream mediators in neutrophils, thus suppressing excessive granulopoiesis as seen in type 2 diabetes." (PMID 39875729, 2025).
acute coronary syndrome (5 papers, 2008 to 2025). Signs and symptoms related to acute ischemia of the myocardium secondary to coronary artery disease. "The pro-inflammatory properties of S100A9 are supported by the fact that there is co-localization of S100A9 with macrophages/granulocytes in human thrombi and that there is an increase in S100A9 mRNA expression in human platelets in patients with acute coronary syndrome (ACS)." (PMID 29419744, 2018).
acute kidney injury (5 papers, 2006 to 2025). Sudden and sustained deterioration of the kidney function characterized by decreased glomerular filtration rate, increased serum creatinine or oliguria. "The nomogram-histogram and decision curve analysis (DCA) showed that CatB and S100-A9 were predicted factors for renal failure in septic patients." (PMID 39049003, 2024). "CatB and S100-A9 were possible predictive factors for preoperative diagnosis of renal failure in septic patients." (PMID 39049003, 2024). "We found S100-A9 to be a key marker in preoperative diagnosis and postoperative prediction of organ dysfunction, especially for renal failure." (PMID 39049003, 2024). "A study indicated a correlation between septic shock and acute kidney injury (AKI), revealing that the genes PTX3, VMP1, OLFM4, SLPI, TIMP1, LCN2, and S100A9 are strongly correlated with novel biomarkers implicated in the onset and progression of sepsis‐associated acute kidney injury (SSAKI)." (PMID 41394771, 2025). "S100-A9 and Cat B were potential predict factors for preoperative prediction of renal failure." (PMID 39049003, 2024). "In clinical studies on patients (including pediatric patients) with acute kidney injury (AKI), DAMPs, specifically S100A8/S100A9 and urine mitochondrial DNA (mtDNA), have been identified as potential diagnostic and prognostic biomarkers, reflecting, for example, the severity of this disease." (PMID 40343200, 2025). "Sepsis may also induce acute kidney injury (AKI), and studies showed that VMP1, SLPI, PTX3, TIMP1, OLFM4, LCN2, and S100A9 genes were markedly correlated with the development and progression of septic-shock-associated AKI." (PMID 36299685, 2022).
bacterial pneumonia (5 papers, 2012 to 2024). Acute infection of the lung parenchyma caused by bacteria (e.g., Streptococcus pneumoniae, Haemophilus influenzae, Chlamydia pneumoniae, Mycoplasma pneumoniae, and Legionella pneumophila). "For example, LTF, MPO, LCN2, and S100A9 are markers of neutrophil degranulation previously associated with bacterial pneumonia." (PMID 39409176, 2024). "As two recently published guidelines clearly made a recommendation against PCT as primary diagnostic biomarker protein, these data further support the potential importance of S100A9 as novel biomarker for bacterial pneumonia." (PMID 37467233, 2023). "In this report, we show that S100A9 is significantly elevated in the lungs of patients with bacterial but not viral pneumonia, suggesting that this alarmin might be a promising new biomarker in bacterial pneumonia." (PMID 37467233, 2023).
chorioamnionitis (5 papers, 2012 to 2023). A morphologic finding indicating inflammation of the fetal sac membranes. "Consistent with its known biological role, several proteomic studies on women with PTL have proposed S100A9 in AF, maternal serum, or cervical fluid as a diagnostic marker for intra-amniotic infection and/or inflammation." (PMID 34710180, 2021). "In spite of a relatively small study group and an arbitrary cut-off based on median expression of S100A8 and S100A9 only, we found a strong correlation between S100A gene expression and clinical conditions that are associated with chorioamnionitis and fetal inflammation." (PMID 32612607, 2020). "Our analysis included inflammatory mediators reported to be associated with chorioamnionitis, preterm labor, and fetal inflammatory response syndrome such as IL-1α, IL-1β, IL-6, TNF-α, S100A8, and S100A9." (PMID 22952869, 2012). "S100a8, S100a9, Il1b, and Mmp8 have been strongly associated with fetal inflammatory response syndrome (FIRS), preterm labor, and chorioamnionitis in preterm infants, further supporting our rat model using IA LPS injections to simulate IAI and a FIRS-like response." (PMID 38481391, 2023). "Based on our findings of S100A monocyte gene upregulation in association with clinical signs of inflammation, we investigated if S100A8 and S100A9 proteins in cord blood could serve as markers for exposure to chorioamnionitis and fetal inflammation." (PMID 32612607, 2020). "In human, high expression of PMN-produced S100A9 was detected in chorioamnionitis and was associated with preterm labour without premature membrane rupture." (PMID 31197179, 2019). "This implies a direct link between exposure to chorioamnionitis and an altered monocyte phenotype characterized by high expression of S100A8 and S100A9 genes." (PMID 32612607, 2020). "In this study, we investigate S100A8, S100A9, and S100A12 gene expression in cord blood monocytes from term healthy infants and preterm infants with exposure to chorioamnionitis or with a fetal inflammatory response." (PMID 32612607, 2020). "Increased levels of calgranulins S100A8, S100A9, and S100A12 have also been detected in the amniotic fluid of chorioamnionitis patients experiencing PTL and/or fetal inflammatory response syndrome." (PMID 22952869, 2012). "Disease outcome was assessed by microbial culture, in situ detection of U. parvum in fetal and utero-placental tissues, grading of chorioamnionitis, and placental gene expression of IL-1α, IL-1β, IL-6, TNF-α, S100A8, and S100A9." (PMID 22952869, 2012). "C57BL/6 infected animals predominantly exhibited mild to moderate chorioamnionitis (P<0.0001), and a significant reduction in placental expression of IL-1α, IL-1β, IL-6, TNF-α, S100A8, and S100A9 compared to sham controls (P<0.02)." (PMID 22952869, 2012). "Conversely, severe protracted chorioamnionitis with cellular necrosis was the predominant lesion phenotype in BALB/c mice, which also exhibited a significant increase in placental expression of IL-1α, IL-1β, IL-6, TNF-α, S100A8, and S100A9 (P<0.01)." (PMID 22952869, 2012). "In this work, we used our model to determine whether GBS-induced chorioamnionitis induces a sexually dichotomous innate inflammatory process driven by IL-1β, IL-1-induced chemokine cytokine-induced neutrophil chemoattractant-1 (CINC-1/CXCL1) attracting PMNs, and PMN-produced S100A9 and MMP-8." (PMID 31197179, 2019).
Cognitive impairment (5 papers, 2014 to 2024). Abnormal cognition is characterized by deficits in thinking, reasoning, or remembering. "Overall, these results suggest that S100A9 is responsible for the neurodegeneration and cognitive deficits in Tg2576 mice." (PMID 24586443, 2014). "Similarly, by using iTRAQ-based proteomics, protein S100-A9 and metalloproteinase-9 (MMP9) are found to be associated with inflammation and cognitive impairment induced by HIV." (PMID 28391008, 2017).
colorectal tumor (5 papers, 2014 to 2024). "In conclusion, our study effectively illustrates the heightened expression of S100A8/S100A9 within colorectal tumor epithelial cells, indicating their crucial role in tumor advancement." (PMID 38817853, 2024). "Previously, we reported the presence of both S100A8-positive and S100A9-positive stromal monocytes in the tumour microenvironment of pancreatic and colorectal tumours." (PMID 30558665, 2018). "S100 Calcium Binding Protein, S100A9, and S100A8 showed more than a threefold increase in expression in over 80% of colorectal tumor tissue samples in our study." (PMID 38979413, 2024).
diabetic nephropathy (5 papers, 2020 to 2025). "This study presents a robust immunoinformatics-to-validation pipeline for identifying serologically detectable B-cell epitopes from HMGB1, S100A8, and S100A9—three key DAMP proteins implicated in diabetic nephropathy." (PMID 41367913, 2025). "Another study found that S100a8 and S100a9 were upregulated in the kidney proteome of mice with diabetic nephropathy (DN)." (PMID 39911133, 2025). "Decreased levels of miR-30b-5p, S100A8, S100A9 and regucalcin have also been described in diabetic nephropathy." (PMID 32849923, 2020).
inflammatory skin disease (5 papers, 2015 to 2025). Inflammatory skin disorders covers a broad category that includes many conditions ranging in severity, from mild itching to grave medical health complications These disorders are common in people of all ages and races. "In particular, S100a8 and S100a9 have been shown to be increased in inflammatory skin diseases, suggesting that the PAC1R KO mice have skin inflammation due to defective aquaporin action." (PMID 36902003, 2023). "It is up-regulated in inflammatory skin disorders, while S100A8 and S100A9 form a complex that displays cytostatic and anti-microbial activities." (PMID 26717000, 2015).
influenza infection (5 papers, 2013 to 2024). "Previous research has shown that inflammation-related factors (IL-1, TNF, CXCL1, CXCL2, S100A8, and S100A9) predominantly express in neutrophils, and neutrophils infiltration largely account for lethal influenza infection." (PMID 35495713, 2022). "Furthermore, LTF and LCN2 also belong to the core genes associated with clinical severity in influenza infections, while LTF and S100A9 were associated with a higher mortality in patients with COVID-19 disease." (PMID 39409176, 2024). "Although S100A9 is classified as a DAMP, using clinically important influenza A virus (IAV) infection model, we show release of S100A9 from “undamaged” cells during IAV infection; which triggered PRR (i.e., TLR) signaling." (PMID 24391503, 2014). "Although invasive fungal infections are not commonly associated with influenza infections, the expression of proteins such as S100A8, S100A9 may also exert antifungal effects." (PMID 23467809, 2013). "Incubation of influenza-infected BALF with neutrophils did not significantly alter the gene expression of cathelicidin, S100A8, S100A9, lactotransferrin, pentraxin-3, and MMP9 (data not shown)." (PMID 23467809, 2013).
invasive ductal carcinoma (5 papers, 2012 to 2022). "S100A8 and S100A9 protein expression are also frequently detected in poorly differentiated invasive ductal carcinoma of breast cancer." (PMID 28051137, 2017).